ENSG00000273961
Gene: Miscellaneous RNA gene on chromosome 7 (27,185,433 to 27,185,530, forward strand). Ensembl gene ENSG00000273961.
Gene Ontology:
Biological process: negative regulation of gene expression
Homologues: Orthologues: mouse Gm56036 (95% identical).